ZNF813 (zinc finger protein 813)
Description:
May be involved in transcriptional regulation.
Synonyms: FLJ16542
Tractability: PROTAC: ubiquitination databases record sites on it.
Gene: Protein-coding gene on chromosome 19 (53,467,703 to 53,496,255, forward strand). Ensembl gene ENSG00000198346.
Subcellular location: Nucleus
Subcellular location (Human Protein Atlas): Vesicles
Gene Ontology:
Molecular function: DNA-binding transcription factor activity, RNA polymerase II-specific; RNA polymerase II cis-regulatory region sequence-specific DNA binding
Biological process: regulation of transcription by RNA polymerase II; regulation of DNA-templated transcription
Cellular component: nucleus
Genetic constraint (gnomAD): Loss-of-function variants: 3 observed, 6.48 expected, observed/expected ratio (o/e) 0.46, 90% interval 0.21 to 1.19. That is too few expected variants to judge how well the gene tolerates losing a copy. Missense variants: 714 observed, 772.15 expected, observed/expected ratio (o/e) 0.92, 90% interval 0.87 to 0.98. Synonymous variants: 227 observed, 257.29 expected, observed/expected ratio (o/e) 0.88, 90% interval 0.79 to 0.99.
Homologues: Orthologues: chimpanzee ZNF813 (98% identical). Paralogues in human: ZNF761 (78% identical), ZNF888 (74% identical), ZNF860 (72% identical), ZNF816 (70% identical), ZNF578 (67% identical), ZNF765 (67% identical), ZNF468 (62% identical), ZNF525 (61% identical), ZNF701 (55% identical), ZNF766 (40% identical).
Diseases named in the same sentence as ZNF813 in open-access papers:
ZNF813 is named in the same sentence as 5 diseases in open-access papers, as found by Europe PMC text mining. Sharing a sentence is not in itself a finding about the gene and the disease. The quoted sentences say what the papers report.
lymph node metastasis (1 paper, 2015). "Correlation was shown between PD-L1 and tumor size and lymph node metastasis, HOXB9 and tumor size, BLNK and perineural invasion, and between ZNF813 and perineural invasion." (PMID 26041877, 2015).
tumor (2 papers, 2015 to 2022). "We also found a correlation between HOXB9 expression and tumor size (p = 0.021) and gender (p = 0.006), BLNK and perineural invasion (p = 0.023) and ZNF813 and perineural invasion (p = 0.029)." (PMID 26041877, 2015).
cancer (1 paper, 2015). A tumor composed of atypical neoplastic, often pleomorphic cells that invade other tissues. "Interestingly, the expression of PD-L1, HOXB9 and ZNF813 were similar to that found in primary tumors from A. C. Camargo Cancer Center, especially in larger tumors." (PMID 26041877, 2015).
ZNF813 also shares sentences with these, for which no sentence is quoted: glioma (1 paper); HIV-1 infection (1).